SETX (senataxin)
Diseases named in the same sentence as SETX in open-access papers (continued):
Sharing a sentence is not in itself a finding about the gene and the disease.
amyotrophic lateral sclerosis (20 papers, 2009 to 2025). Amyotrophic lateral sclerosis (ALS) is a neurodegenerative disease characterized by progressive muscular paralysis reflecting degeneration of motor neurons in the primary motor cortex, corticospinal tracts, brainstem and spinal cord. "Mutations in the SETX gene have been linked to neurodegenerative diseases, such as amyotrophic lateral sclerosis (ALS4) and ataxia with oculomotor apraxia type 2 (AOA2), underscoring the importance of senataxin in both neuronal health and genomic integrity." (PMID 39594478, 2024). "Mutations in SETX are also associated with the phenotype of juvenile-onset Amyotrophic Lateral Sclerosis (ALS)." (PMID 35203940, 2022). "At the same time, we reported dominant SETX mutations linked to a rare form of juvenile Amyotrophic Lateral Sclerosis (ALS), known as ALS4." (PMID 34263556, 2021). "Senataxin is mutated in juvenile forms of Ataxia and amyotrophic lateral sclerosis (ALS), while RNaseH2 in the neuroinflammatory Aicardi–Goutières disorder." (PMID 25972894, 2015). "Ataxia with oculomotor apraxia 2 (AOA-2) and amyotrophic lateral sclerosis (ALS4) are neurological disorders caused by mutations in the gene encoding for senataxin (SETX), a putative RNA:DNA helicase involved in transcription and in the maintenance of genome integrity." (PMID 29416069, 2018). "Mutations in SETX result in either of two distinct neurodegenerative disorders: recessive mutations are responsible for AOA2, while dominant mutations result in a juvenile form of amyotrophic lateral sclerosis (ALS) called ALS4." (PMID 38390227, 2023). "SETX is associated with autosomal-dominant juvenile amyotrophic lateral sclerosis type 4 (ALS; MIM: 602433) and autosomal recessive ataxia with ocular apraxia type 2 (AOA2; MIM: 606002)." (PMID 37327344, 2023). "Diseases involving SETX mutations are usually associated with the nervous system, including ataxia with oculomotor apraxia type 2 (AOA2) and a juvenile form of amyotrophic lateral sclerosis named ALS4." (PMID 35202347, 2022). "In addition, dominant missense variants in SETX cause amyotrophic lateral sclerosis (ALS) with juvenile onset (ALS4), suggesting that gain-of-function leads to ALS4." (PMID 35326432, 2022).
Oculomotor apraxia (15 papers, 2006 to 2023). Ocular motor apraxia is a deficiency in voluntary, horizontal, lateral, fast eye movements (saccades) with retention of slow pursuit movements. "Autosomal recessive inherited ataxia with oculomotor apraxia type 2 (AOA2), caused by SETX gene mutations, is characterized by early-onset, progressive cerebellar ataxia, peripheral neuropathy, oculomotor apraxia and elevated serum α-fetoprotein (AFP)." (PMID 36438189, 2022). "Senataxin (SETX) was initially identified as a causative gene for severe early-onset ataxia with oculomotor apraxia (AOA2), which is the second most common recessive ataxia after Freidreich's ataxia." (PMID 26213621, 2015). "Interestingly, in one family with pathogenic variants in SETX and one in PNKP, oculomotor apraxia was not present." (PMID 35326432, 2022).
Ataxia‐ocular apraxia 2 (10 papers, 2011 to 2025). "SETX missense mutations have also been identified as a causative for neurodegenerative condition ataxia-ocular apraxia 2 (AOA2) through a loss-of-function mechanism." (PMID 35646086, 2022). "SETX is associated with autosomal recessive spinocerebellar ataxia-1 and ataxia-oculomotor apraxia-2." (PMID 27120335, 2016). "For example, Senataxin (SETX) is a 5′→3′ helicase that resolves R-loops, especially during transcription termination; mutations in SETX cause AOA2 (ataxia oculomotor apraxia 2) and ALS4, disorders marked by R-loop accumulation in neurons." (PMID 40332372, 2025). "In addition, positional cloning technique reveals that the mutations in SETX gene in the locus also associated with autosomal recessive spinocerebellar ataxia-1 (SCAR1), which is also referred to ataxia-ocular apraxia-2 (AOA2)." (PMID 23941283, 2013). "Mutations in the SETX gene are associated with the progressive neurological disorders Amyotrophic lateral sclerosis 4 (ALS4) and Ataxia with oculomotor apraxia 2 (AOA2), highlighting the importance of SETX functions in the cell." (PMID 39119900, 2024).
Cerebellar atrophy (9 papers, 2008 to 2024). Cerebellar atrophy is defined as a cerebellum with initially normal structures, in a posterior fossa with normal size, which displays enlarged fissures (interfolial spaces) in comparison to the foliae secondary to loss of tissue. "We identified a novel SETX homozygous c.5308_5311delGAGA mutation that co-segregates with ARCA with cerebellar atrophy and raised AFP." (PMID 18405395, 2008).
juvenile amyotrophic lateral sclerosis (9 papers, 2011 to 2025). Juvenile amyotrophic lateral sclerosis (JALS) is a very rare severe motor neuron disease characterized by progressive upper and lower motor neuron degeneration causing facial spasticity, dysarthria, and gait disorders with onset before 25 years of age. "For example, SETX, a DNA repair factor associated with oculomotor apraxia type 2 (AOA2) and juvenile amyotrophic lateral sclerosis (ALS4), has been widely accepted as an R-loop processing helicase." (PMID 40271193, 2025). "Mutations in SETX have been reported to be associated with ataxia-ocular apraxia-2 (AOA2) and an autosomal dominant form of juvenile amyotrophic lateral sclerosis (ALS4)." (PMID 25519331, 2014). "Heterozygous missense substitutions in SETX can give rise to dominant juvenile amyotrophic lateral sclerosis (ALS4, OMIM 602433)." (PMID 23947751, 2013). "Of note, mutations in the helicase domain of the human SEN1 gene ortholog SETX (encoding Senataxin) cause the neurodegenerative diseases, Ataxia with Oculomotor Apraxia Type II (AOAII), and juvenile amyotrophic lateral sclerosis (ALS4)." (PMID 21211720, 2011).
motor neuron disease (9 papers, 2009 to 2024). "In our case, we investigated the SETX gene, e.g., as found in association with motor neurone disease or the Charcot–Marie–Tooth syndrome." (PMID 37885757, 2023). "To further assess the role of SETX in motor neuron disease and neurodegeneration, we examined Drosophila expressing transgenic human SETX under the control of the UAS-Gal4 system." (PMID 37845749, 2023). "SETX mutations in ALS4, a rare juvenile-onset familial form of ALS, presumably cause a gain-of-function, as loss-of-function mutations in the SETX gene are responsible for autosomal recessive Ataxia with Oculomotor Apraxia type 2 (AOA2), and AOA2 carriers do not develop motor neuron disease." (PMID 38802624, 2024).
neuropathy (7 papers, 2013 to 2022). A disorder affecting the nervous system that manifests with pain, tingling, numbness, and/or muscle weakness. "Both PNKP and SETX were universally associated with neuropathy, but not with AOA; the reason why AR4 had not been previously tested for SETX." (PMID 35326432, 2022). "However, the precise molecular functions of SETX, and how mutations in this gene lead to AOA2 neuropathy, remain largely unknown." (PMID 35042798, 2022). "Our data suggest that senataxin functions at DSBs in order to limit translocations and ensure cell viability, providing new insights on AOA2/ALS4 neuropathies." (PMID 29416069, 2018).
Onset (5 papers, 2011 to 2021). The age group in which disease manifestations appear. "Mutations in senataxin (SETX) gene were described as a rare underlying cause of autosomal dominant form of juvenile‐onset FALS." (PMID 30052327, 2018). "Another juvenile-onset ALS is autosomal dominant ALS4 linked to mutations in the SETX gene encoding senataxin, which is thought to possess DNA/RNA helicase acitivty." (PMID 22272119, 2011). "ALS4 is a rare autosomal dominant form of juvenile-onset ALS due to mutations in SETX." (PMID 26843957, 2016). "Although SETX variants have been initially discovered in juvenile-onset ALS patients, reports have since described damaging alleles in patients with adult-onset ALS." (PMID 33414559, 2021).
Spinocerebellar ataxia with axonal neuropathy type 2 (5 papers, 2013 to 2025). "Recessive mutations in SETX cause Spinocerebellar Ataxia, Autosomal Recessive 1 (SCAR1, OMIM 606002)." (PMID 23947751, 2013).
autosomal dominant proximal spinal muscular atrophy (3 papers, 2018 to 2022). A group of rare, genetic, motor neuron disease characterized by childhood or adult onset progressive, predominantly proximal, muscular weakness and wasting. "Other neurological diseases, including tremor-ataxia syndrome, autosomal dominant proximal spinal muscular atrophy, and Charcot-Marie-Tooth disease have also been linked with mutations in the SETX gene (62, –64)." (PMID 35042798, 2022).
breast carcinoma (3 papers, 2022 to 2023). "In addition to dysregulated expression, human tumors are also characterized by mutations in SETX gene and a tumor suppressive screening identified SETX as a mutated gene in breast cancer." (PMID 37147318, 2023).
Chorea (3 papers, 2017 to 2023). Chorea (Greek for 'dance') refers to widespread arrhythmic involuntary movements of a forcible, jerky and restless fashion. "The FUS, VCP, and SETX genes have low mutation frequencies in ALS with chorea; however, the more subtle features of ALS with chorea due to mutations in these genes need to be further explored." (PMID 36596053, 2022). "Further genetic investigation, including SETX and other chorea-related genes (i.e., ADCY5, PRNP, and VPS13A) are needed, but are lacking due to limitations of laboratory conditions." (PMID 36596053, 2022). "ALS with chorea can be caused by abnormal amplification of a CAG sequence in the HTT gene and FUS, VCP, and SETX mutations." (PMID 36596053, 2022). "The FUS, VCP, and SETX genes also have low mutation frequencies in patients with ALS and chorea." (PMID 36596053, 2022).
Fanconi anemia (3 papers, 2022 to 2025). Fanconi anemia (FA) is a hereditary DNA repair disorder characterized by progressive pancytopenia with bone marrow failure, variable congenital malformations and predisposition to develop hematological or solid tumors. "A synthetic lethal interaction is reported between the R-loop helicase Senataxin (SETX) and Fanconi anemia pathway proteins, with SETX deficiency increasing replication stress-induced chromosome fragility & activation of mitotic DNA synthesis." (PMID 36543851, 2022). "At centromeres, the resolution of DNA secondary structures has been shown to involve the DNA2 nuclease/helicase while the homologous recombination (HR) and Fanconi anemia (FA) factor BRCA1 has been proposed to limit centromeric R-loop-associated instability by recruiting SETX." (PMID 38038252, 2024). "Several factors have been involved in the prevention of R-loop accumulation and their resolution, including DNA topoisomerases I and II, the DNA helicases Pif1, DHX9 and Senataxin (SETX), Fanconi Anemia (FA) proteins, and RNase H." (PMID 38038252, 2024). "Here we identify a synthetic lethal interaction between SETX and proteins of the Fanconi anemia (FA) pathway." (PMID 36543851, 2022). "SETX (senataxin), BLM (Bloom syndrome), WRN (Werner syndrome), and FANCM (Fanconi anemia complementation group M) are identified to possess proficient abilities for unwinding DNA-RNA hybrids." (PMID 40713627, 2025).
Infertility (3 papers, 2013 to 2022). "The role of SETX in azoospermia and infertility was subsequently determined by histopathological examinations of testes from AOA2 patients and SETX knockdown mice." (PMID 36438189, 2022).
juvenile ALS (3 papers, 2020 to 2022). "Furthermore, more genes and terms related to RNA polymerase II transcription were downregulated by Combo in sALS compared with CTL, including SETX, a helicase that modulates RNA polymerase II binding to chromatin, known to be associated with juvenile ALS." (PMID 36083004, 2022). "Mutations in SETX are linked to juvenile ALS (ALS type 4), suggesting that neurodegeneration may be caused by defects in R-loop metabolism." (PMID 32989039, 2020).
liposarcoma (3 papers, 2011 to 2023). A usually painless malignant tumor that arises from adipose tissue. "These include the genes codingfor alsin (ALS2), vesicle associated membrane protein B (VAPB), senataxin (SETX), TAR-DNA-bindingprotein (TDP-43), fused in sarcoma or translocated in liposarcoma(FUS/TLS), and optineurin (OPTN)." (PMID 21541368, 2011). "ALS models are commonly based on mutant superoxide dismutase 1 (SOD1), TAR DNA-binding protein 43 (TDP-43), fused in sarcoma or translocated in liposarcoma (FUS), the chromosome 9 open reading frame 72 (C9orf72) gene, ubiquilin 2 (UBQLN2), matrin 3 (MATR3), and senataxin (SETX)." (PMID 36672187, 2023).
male infertility (3 papers, 2013 to 2025). The inability of the male to effect fertilization of an ovum after a specified period of unprotected intercourse. "SETX, the gene that encodes Senataxin, is required for proper mammalian meiosis, as SETX-/- mutants exhibit male infertility, as well as defects in DSB repair and crossover formation, accumulation of DNA:RNA hybrids and increased apoptosis during prophase I." (PMID 41379861, 2025). "Senataxin disruption is associated with male infertility in humans, and Setx-/- male mice are infertile resulting from arrest at the pachytene stage in meiosis I." (PMID 35133275, 2022). "Mouse mutants lacking Senataxin exhibit male infertility and defects in double strand break repair." (PMID 41379861, 2025).
motor neuron degeneration (3 papers, 2015 to 2022). "ALS4 SETX mice develop neuromuscular phenotypes and motor neuron degeneration with key ALS features of TDP-43 nuclear clearance and cytosolic mislocalization." (PMID 34922620, 2021).
polyneuropathy (3 papers, 2021 to 2023). A disease or disorder affecting more than one nerve. "We identified two unrelated patients with the same de novo c.23C > T (p.Thr8Met) variant in SETX presenting with an early-onset, severe polyneuropathy." (PMID 34922620, 2021). "With NGS application, we identified a novel heterozygous mutation of SETX in a case of ARCA with polyneuropathy and elevated AFP without OMA in Taiwan." (PMID 35203940, 2022).
Telangiectasia (3 papers, 2015 to 2025). Telangiectasias refer to small dilated blood vessels located near the surface of the skin or mucous membranes, measuring between 0.5 and 1 millimeter in diameter. "In addition, senataxin was recently found to undergo ataxia telangiectasia and Rad3–dependent phosphorylation, and this phosphorylation was reported to be important for senataxin association with sex chromosomes during meiosis." (PMID 40540553, 2025). "However, patients with AOA2/4 do not exhibit telangiectasia, and our patients did neither carry putatively causative SETX nor PNKP variants." (PMID 33779842, 2021).
Alzheimer disease (2 papers, 2022). A progressive, neurodegenerative disease characterized by loss of function and death of nerve cells in several areas of the brain leading to loss of cognitive function such as memory and language. "SETX mutations have been detected also in Charcot Marie Tooth (CMT), distal hereditary motor neuropathy (dHMN), childhood apraxia of speech, and Alzheimer’s disease." (PMID 36553628, 2022). "Exceptions included SETX and Dopaminergic synapse (PFDR ≤ 0.00021), and multiple pathways perturbed by the E2F family of transcription factors, such as E2F and Alzheimer’s disease (PFDR ≤ 0.0065)." (PMID 36271102, 2022). "Moreover, three signals involved the THAP1 gene set (paired with Alzheimer’s disease, ALS and viral infection) and four involved the SETX gene set (paired with Alzheimer’s, Parkinson’s, Huntington’s and ALS)." (PMID 36271102, 2022).
Azoospermia (2 papers, 2021 to 2022). Absence of any measurable level of sperm,whereby spermatozoa cannot be observed even after centrifugation of the semen pellet. "The phenotype observed (total arrest of spermatogenesis and the presence of γH2AX foci on apparently synapsed autosomes) suggests that SETX downregulation could partially explain the azoospermia observed in this translocated boar." (PMID 34440311, 2021).
colon adenocarcinoma (2 papers, 2023 to 2025). "Tumors with the highest rate of SETX mutations are uterine endometrial carcinoma (13,23%), skin melanoma (7,6%) and colon adenocarcinoma (6,23%)." (PMID 37147318, 2023). "Remarkably, the early onset of colonic polyps and colon adenocarcinoma (one individual with colon adenocarcinoma is 35‐year‐old) raises the possibility that SETX gain of function mutations might be an early event accelerating tumor onset." (PMID 37147318, 2023).
colon carcinoma (2 papers, 2022 to 2023). "We detected a significant increase in spontaneous chromosome fragility in SETX-depleted cells as compared to control HCT116 colon cancer cells." (PMID 36543851, 2022). "Three AOA2-related SETX mutations, Q868X, R1363X, and P413L have been reported in Uterine Carcinoma, colon carcinoma and skin melanoma, respectively, suggesting that loss of SETX function might be beneficial for tumor development and progression." (PMID 37147318, 2023).
distal motor neuropathy (2 papers, 2021 to 2024). "WGCNA data from the whole blood of Patient 2 and a control patient who had a distal motor neuropathy and a distinct rare variant in SETX (p.Gly2172Asp), were compared to the ALS4 disease-specific signature derived from mouse and human as defined above." (PMID 34922620, 2021).
head and neck cancer (2 papers, 2022 to 2025). A primary or metastatic malignant neoplasm affecting the head and neck. "We next examined SETX and ZPR1 expression in HPV-positive cervical and head and neck cancers using mRNA data from the TCGA database." (PMID 41305523, 2025). "Analysis of TCGA datasets revealed that ZPR1, but not SETX, mRNA expression is significantly reduced in HPV-positive cervical and head and neck cancers." (PMID 41305523, 2025).
Juvenile onset (2 papers, 2022 to 2024). Onset of signs or symptoms of disease between the age of 5 and 15 years. "Several pathogenic SETX mutations have been reported linking SETX proteinopathy with juvenile-onset ALS." (PMID 35563044, 2022).
lung carcinoma (2 papers, 2018 to 2021). "Next, we looked for evidence of links between hypoxia and SETX in cancer patients, using The Cancer Genome Atlas (TCGA) colorectal and lung cancers datasets." (PMID 34140498, 2021). "In LUAD of Pan-Lung Cancer cohort, mutations in GMPPA, DNAJC2, and MMRN2 showed significant negative associations with survival of patients while mutations in DRD3 and SETX showed significant positive association with survival." (PMID 30419062, 2018). "In LUAD of Pan-Lung Cancer cohort, mutations in DNAJC2, GMPPA, MMRN2, DRD3, and SETX were significantly associated with survival status, and those in DNAJC2, MMRN2, and SETX were significantly associated with overall survival." (PMID 30419062, 2018).